AHR (aryl hydrocarbon receptor)
Diseases named in the same sentence as AHR in open-access papers (continued):
Sharing a sentence is not in itself a finding about the gene and the disease.
psoriasis (continued). "In skin biopsies from psoriasis patients, a similar impact of AhR on autophagy and inflammation was observed." (PMID 32235789, 2020). "M5-stimulated keratinocytes, an in vitro model of psoriasis, revealed a particularly strong relationship between AhR and autophagy." (PMID 32235789, 2020). "Taken together, AhR and autophagy exhibited a reverse relationship in keratinocytes, and this phenomenon was particularly pronounced in the in vitro psoriasis model." (PMID 32235789, 2020). "In skin biopsies from psoriasis patients, a similar relationship was observed, as well as cross-talk between AhR and autophagy induced inflammation." (PMID 32235789, 2020). "A particularly strong interaction between AhR and autophagy was observed in proinflammatory cytokines-stimulated keratinocytes, an in vitro model of psoriasis." (PMID 32235789, 2020). "In human psoriasis skin lesions, the level of AhR and CYP1A1 proteins and transcripts was upregulated, while LC3 was downregulated at both mRNA and protein level, compared to controls." (PMID 32235789, 2020). "This study explored the effects of AhR activation on autophagy in human keratinocytes, and the relevance of AhR and autophagy in psoriasis pathogenesis." (PMID 32235789, 2020). "Chronic inflammatory skin disorders emerge as outcome of diverse environmental and immune factors, and diseases such as psoriasis and atopic dermatitis are characterized by dysbalanced AhR signaling." (PMID 31350436, 2019). "A selective AHR agonist, tapinarof is currently being studied because this medicinal agent improves both psoriasis and AD in which different pathomechanisms operate (the TNF-α/IL-23/IL-17 axis in psoriasis and IL-4/IL-13 signaling in AD)." (PMID 31683543, 2019). "As AHR predominantly regulates the immune balance of Th17/22 and Treg cells, AHR is expected to play a significant role in psoriasis." (PMID 31683543, 2019). "The purpose of this article is to summarize the diverse action of AHR signaling in balancing skin homeostasis and to elucidate the fundamental mechanisms of therapeutic AHR potentials in the treatment of AD and psoriasis." (PMID 31683543, 2019). "Recent clinical trials have shown that the topical AHR agonist tapinarof successfully improves clinical symptoms of atopic dermatitis and psoriasis." (PMID 29866992, 2018). "Many genes that are dysregulated during psoriasis are increased after AHR antagonist exposure or in AHR−/− murine models, which results in excessive inflammatory response." (PMID 30513921, 2018). "The list of AhR-modulated genes was reduced to 41 genes belonging to the “psoriasis transcriptome,” which were mainly upregulated in untreated L skin (psoriasis-upregulated genes are shown in bold)." (PMID 24909886, 2014). "Here we show that the aryl hydrocarbon receptor (AhR), a transcription factor that senses environmental stimuli, modulates pathology in psoriasis." (PMID 24909886, 2014). "A luciferase reporter assay demonstrated that the extract activated AhR in the 2D psoriasis model." (PMID 42050003, 2026). "Clinical studies have confirmed significant imbalances in Trp metabolism in the peripheral blood and skin lesion tissues of psoriasis patients: On one hand, levels of protective indole metabolites with AhR-activating activity (e.g., IPA, IAld) are markedly reduced." (PMID 41425939, 2025). "Interestingly, we found excessive CYP1A1 enzymatic activity in in vitro-expanded Th17 cells from psoriasis patients, suggesting a possible dysregulation of the AHR/CYP1A1 axis in psoriasis leading to reduced AHR activation." (PMID 40004095, 2025). "Studies in mice have underscored the importance of finely tuning AhR signaling in the skin: complete genetic deletion of Ahr results in more severe psoriasis-like inflammation, while constitutively active AhR in keratinocytes causes alterations resembling atopic dermatitis." (PMID 40162433, 2025).
psoriasis (continued). "Indole activation of AhR is known to regulate host-microbe interactions and immune function, while research has demonstrated that AhR activation through indoles shows significant therapeutic promise for inflammatory skin conditions, including psoriasis and atopic dermatitis." (PMID 40723482, 2025). "In conclusion, our study identified an AhR-Ovol1-Id1 regulatory axis in keratinocytes that governs both epidermal and immune homeostasis against AD-inducing allergens and pathogens while also implicating a similar mechanism in psoriasis." (PMID 39939818, 2025). "Indeed, the therapeutic relevance of targeting the AhR has been underscored by the recent clinical approval of tapinarof, a selective AhR agonist, for the treatment of psoriasis." (PMID 41321307, 2025). "Recently, newer topical agents such as topical aryl hydrocarbon receptor modulators and topical phosphodiesterase-4 inhibitors are increasingly utilized in psoriasis treatment, but may be limited in terms of cost effectiveness." (PMID 40584948, 2025). "The expression of AhR is modified in psoriasis, influencing the pathogenesis of the disease." (PMID 40574044, 2025). "In May 2022, 1% tapinarof was FDA-approved for mild-to-moderate adult plaque psoriasis, making it the first-in-class AHR modulating drug, as well as the first novel topical treatment for psoriasis developed in 25 years." (PMID 40004095, 2025). "Our study highlights a keratinocyte-intrinsic AhR-Ovol1-Id1 regulatory axis that functions at the environment-barrier-immune interfaces to protect skin homeostasis against skin inflammation and implicates new therapeutic targets for both AD and psoriasis." (PMID 39939818, 2025). "Tapinarof and other AhR modulators could open up new perspectives in the treatment of psoriasis and other inflammatory skin diseases." (PMID 40574044, 2025). "However, the same study reports decreased AHR protein expression in lesional versus healthy skin in their own small independent cohorts of psoriasis patients and healthy controls." (PMID 40004095, 2025). "Finally, tapinarof, a naturally derived AHR activator produced by bacterial symbionts of nematodes, activates the AHR pathway to promote both anti-inflammatory and homeostatic functions in the skin, and has been approved for topical use in psoriasis." (PMID 40004095, 2025). "Aryl hydrocarbon receptor (AhR), an environment-sensing xenobiotic receptor and ligand-activated transcription factor vital for skin immune homeostasis and barrier maintenance, has attracted attention as a therapeutic target for both AD and psoriasis." (PMID 39939818, 2025). "Furthermore, PM and O3 can promote Th17 differentiation through AhR‐dependent pathways, potentially exacerbating psoriasis." (PMID 41414795, 2025). "Moreover, increased enzymatic activity of CYP1A1 has been demonstrated in the skin of psoriasis patients, which affects the reduction of aryl hydrocarbon receptor (AHR) pathway activation, which acts anti-inflammatory." (PMID 39825220, 2025). "A selective AHR agonist was investigated as an agent that may improve both psoriasis and atopic dermatitis." (PMID 38907248, 2024). "These lines of evidence indicate that AhR signaling is overactivated in psoriasis." (PMID 39296901, 2024). "Furthermore, researchers have detected overexpression of AhR in lesional KCs from psoriasis patients." (PMID 39296901, 2024). "Notably, our experiments identified AHR as a therapeutic target of IDG, both in vivo and ex vivo, demonstrating that IDG can treat psoriasis by activating AHR." (PMID 39465158, 2024). "Research has demonstrated that abnormal interactions between keratinocytes (KCs) and the immune system are pivotal in the pathogenesis of psoriasis, with the aryl hydrocarbon receptor (AhR) and nuclear factor (NF)-κB serving as critical mediators of these interactions." (PMID 39465158, 2024).
psoriasis (continued). "Aryl hydrocarbon receptor (AhR) regulates autophagy through the nuclear factor kappa-B (NF-κB)/mitogen-activated protein kinase (MAPK) signaling pathway leading to psoriasis, suggesting that AhR signaling and autophagy are involved in the pathogenesis of psoriasis." (PMID 39559368, 2024). "This suggests that the AhR signaling pathway may play a role as a “double-edged sword” in psoriasis, and in-depth exploration of its role is conducive to the clinical diagnosis and treatment of psoriasis." (PMID 39296901, 2024). "Moreover, the recently approved drug Tapinarof acts as an AHR agonist and regulates the expression of Th17 cells; Tapinarof has shown success as a topical treatment for psoriasis." (PMID 39337637, 2024). "The AhR agonist tapinarof has been used to treat psoriasis and atopic dermatitis." (PMID 38361944, 2024). "According to the available data, PM2.5, PM10, and surface ozone (O3) may play essential roles in psoriasis development via aryl hydrocarbon receptor (AHR) activation, leading to increased Th-17 differentiation." (PMID 39519223, 2024). "Further investigation into whether IDG NE mitigates IMQ-induced psoriasis-like skin inflammation through the activation of AhR signaling was conducted via Western blotting analysis to detect CYP1A1 protein expression in skin lesion tissues." (PMID 39465158, 2024). "While AHR stimulation may increase the inflammatory response, and AHR antagonists are currently under investigation as a therapeutic option for psoriasis, the AHR pathway also plays a regulatory role in preventing the overexpression of inflammatory cytokines." (PMID 39337637, 2024). "This suggests that IDG may exert its anti-inflammatory effects in psoriasis by modulating the AHR/NF-κB signaling pathway." (PMID 39465158, 2024). "AhR agonists have ameliorated imiquimod-induced psoriasis in mouse models and may be a therapeutic target." (PMID 37623895, 2023). "While many FDA-approved drugs activate AhR, there is currently only one drug approved for targeting the function of AhR, with the relatively recent approval of tapinarof as an immunomodulatory AhR agonist for psoriasis." (PMID 37106727, 2023). "The activation of the aryl hydrocarbon receptor (AhR) promotes the expression of anti-inflammatory cells and anti-inflammatory factors and inhibits the immune response, and AhR inhibitors have become key therapeutic agents for the treatment of psoriasis." (PMID 37762693, 2023). "The Aryl hydrocarbon receptor (AhR) is a transcription factor that is dependent on cytosolic ligands and is expressed in various types of skin cells, playing a role in the pathogenesis of inflammatory skin diseases, including psoriasis." (PMID 37942312, 2023). "Furthermore, tapinarof exhibits direct binding to the aryl hydrocarbon receptor (AhR), leading to a reduction in the production of inflammatory cytokines, including IL-17A, IL-17F, IL-22, IL-23, and IL-1β, as demonstrated in a psoriasis-like mouse model." (PMID 38288335, 2023). "AhR is the cytosolic ligand-activated receptor and transcription factor that is mainly expressed in skin cells, and AhR in cutaneous vascular endothelial cells (VECs) is crucial for the emergence of psoriasis." (PMID 37228538, 2023). "This indicates that tapinarof attenuates psoriasis and atopic dermatitis via activation of AhR." (PMID 36983027, 2023). "Conversely, prolonged and heightened uncontrolled AhR activation induced by pathological ligands, including TCDD and BaP, elicits inflammatory responses associated with cutaneous inflammatory diseases, such as psoriasis." (PMID 38288335, 2023). "As such, AHR-mediated regulation of the IL-33–IL-37 axis may lead to new therapeutic strategies for AD and psoriasis." (PMID 37834081, 2023). "Of note, topical AhR-modulating medications are being developed and tested for the management of AD and psoriasis, and future research can ascertain whether they can be used to alleviate pollution-related AD symptoms." (PMID 36767891, 2023).
psoriasis (continued). "Likewise, quinolinic acid, an AHR agonist derived from skin microbiota, negatively regulates NLRP3 inflammasome through the AHR-Trp pathway in Psoriasis." (PMID 37942478, 2023). "Taken together, our findings provide the first evidence that tapinarof and GFF could have potential to prevent IL-33-overexpressing disorders such as AD and psoriasis via the AHR/IL-37 axis." (PMID 35663970, 2022). "It is characterized by the observation of unregulated AhR expression in psoriasis patients." (PMID 35625824, 2022). "It was reported that tapinarof and laquinimod could significantly target the AhR to treat multiple sclerosis, atopic dermatitis, and psoriasis." (PMID 36601108, 2022). "Several lines of research suggest that the AhR pathway may be a valuable target for diseases, e.g., multiple sclerosis, inflammatory bowel disorders, psoriasis, cancer, and stem cell transplantation, although caution is still advised." (PMID 36601108, 2022). "The aryl hydrocarbon receptor (AhR) plays a role in the pathogenesis of psoriasis, and tapinarof, a novel, first‐in‐class, small molecule topical therapeutic AhR‐modulating agent has been recently approved by the FDA for the topical treatment of plaque psoriasis in adults." (PMID 36226669, 2022). "Similarly, an in-vivo model of imiquimod-induced psoriasis exhibits that, instead of hematopoietic cells, AHR in keratinocytes limits inflammation." (PMID 36601108, 2022). "Thus, the expression of CYP1A1 is significantly decreased in lesional skin, suggesting that activation of the AHR pathway is impaired in psoriasis." (PMID 33385398, 2021). "Nevertheless, the role of AhR in psoriasis is controversial." (PMID 33499346, 2021). "Recent studies indicate that the use of IL-17 blockers in an IMQ-induced psoriasis-like skin model is not sufficient to decrease the formation of skin lesions in AHR-deficient mice." (PMID 33499346, 2021). "In this study, we hypothesize that CYP1A1 feedback regulates skin inflammation and that upregulation of its enzymatic activity may occur in patients with psoriasis, disrupting the anti-inflammatory effect mediated by physiological AHR signaling." (PMID 33385398, 2021). "In recent years, the involvement of AhR in the pathogenesis of psoriasis has been reported." (PMID 34944067, 2021). "One study showed that IL-8 was upregulated in Benzo(a)pyrene (BaP) treated human keratinocytes in a AhR-ROS-dependent regulation, which might explain the exacerbation of certain skin diseases such as psoriasis and acne due to cigarette smoking." (PMID 34574641, 2021). "In addition to current oral treatments and biologics, a new treatment option for psoriasis is now being developed, such as retinoic-acid-receptor-related orphan nuclear receptor γt inhibitors, IL-36 receptor antagonist, or aryl hydrocarbon receptor agonist." (PMID 33804147, 2021). "Currently, Tapinarof is a topical AhR agonist on the market used to treat both AD and psoriasis." (PMID 35008717, 2021). "The expression of AhR was increased in the lesional skin of psoriasis in our previous study." (PMID 34884515, 2021). "In contrast, the use of AhR antagonists increased inflammation and induced the expression of psoriasis-associated genes in non-lesional skin." (PMID 34299118, 2021). "We also examined whether tapinarof, a potent AHR activator that is utilized clinically in the treatment of psoriasis and atopic dermatitis, has the same effect as Glyteer on IL-4-induced upregulation of IL-33 expression." (PMID 32214018, 2020). "Here, we first review new insights regarding the pathogenesis of psoriasis, as it relates to DCs, Langerhans cells, macrophages, the signal transducer and activator of transcription 3 pathway, and aryl hydrocarbon receptor in cutaneous vascular endothelial cells." (PMID 33050592, 2020).
psoriasis (continued). "Both AhR signaling and autophagy act as skin homeostatic rheostats sensing environmental stimuli, and evidence suggests that AhR signaling and autophagy are involved in the pathogenesis of chronic inflammatory skin disease, such as psoriasis." (PMID 32235789, 2020). "Anti-psoriatic effects of other topical treatment options have recently been linked to modulation of the aryl hydrocarbon receptor (AhR) and AhR may play a role in pathogenesis of psoriasis." (PMID 32484435, 2020). "To verify the impact of environmental factors on psoriasis, we focused on AhR effects on autophagy." (PMID 32235789, 2020). "Our data suggests that AhR-induced inhibition of autophagy may be involved in the pathogenesis of chronic inflammatory disorders such as psoriasis." (PMID 32235789, 2020). "In addition, AhR in cutaneous vascular endothelial cells (VECs) also plays an important role in the development of psoriasis." (PMID 33050592, 2020). "Furthermore, AhR regulates the balance of the Th17/22 system, which is important for developing psoriasis." (PMID 33050592, 2020). "Although, the functional roles of FABP4/5 remain to be defined, their activity may be juxtaposed to that of AhR, the activity of which can dampen psoriasis-like symptoms." (PMID 31379871, 2019). "Notably, recent phase II, randomized dose-finding studies have demonstrated that topical application of the natural AHR agonist tapinarof is efficacious and well tolerated in patients with AD and psoriasis." (PMID 31683543, 2019). "Notably, AHR agonists, such as tapinarof, are currently used as therapeutic agents in psoriasis and atopic dermatitis." (PMID 31683543, 2019). "In this review, we summarize recent topics on AHR related to atopic dermatitis and psoriasis." (PMID 31683543, 2019). "The result is compatible with previous reports, as AhR-deficiency in mice resulted in reduced IL-22-secreting CD4+ T cells and more specifically, a psoriasis model demonstrated the requirement of AhR for IL-22 production by Th17, but not by ILC3 and γδ+ T cells." (PMID 30944419, 2019). "This review will focus on the role of AHR in modulating immune/inflammatory responses to pathogens, central nervous system diseases, the gut microbiome, inflammatory bowel disease, rheumatoid arthritis, and psoriasis." (PMID 30513921, 2018). "In order to address whether the AhR pathway has a role in human skin pathology, we investigated whether AhR activation via the agonist FICZ or inhibition via the antagonist CH-223191 would cause transcriptional changes in psoriasis-related genes." (PMID 24909886, 2014). "However, in mouse models of psoriasis blocking of the AhR unexpectedly resulted in exacerbation of the disease." (PMID 25203682, 2014). "Lack of Ahr causes hyperinflammation, whereas deliberate AhR activation with the endogenous ligand FICZ ameliorates the inflammatory profile in both human psoriasis samples and the mouse model of psoriasiform skin inflammation." (PMID 24909886, 2014). "Similarly, the activation of AHR by pollutants induces inflammation in exposed skin, but therapeutic AHR-modulating agents such as tapinarof show anti-inflammatory effects in inflammatory disorders such as AD and psoriasis." (PMID 39399487, 2024). "However, the emergence of the AHR–microbiota axis prompted us to expand insights into other GI diseases, and AHR activity-related diseases including Alzheimer’s disease, arthritis, cardiovascular disease, psoriasis, and so on." (PMID 37942478, 2023). "Moreover, modulated by AhR, autophagy can lead to skin inflammation in human keratinocytes via the p65NF-κβ/p38MAPK signaling pathways, suggesting that AhR signaling and autophagy may contribute to psoriasis-related inflammation." (PMID 37445680, 2023). "Therefore, AHR-mediated regulation of the IL-33–IL-37 axis may lead to new therapeutic strategies for the treatment of AD and psoriasis." (PMID 37834081, 2023).